NKX6-1 (NK6 homeobox 1)
Description:
Transcription factor which binds to specific A/T-rich DNA sequences in the promoter regions of a number of genes. Involved in the development of insulin-producing beta cells in the islets of Langerhans at the secondary transition (By similarity). Together with NKX2-2 and IRX3 acts to restrict the generation of motor neurons to the appropriate region of the neural tube. Belongs to the class II proteins of neuronal progenitor factors, which are induced by SHH signals (By similarity).
Synonyms: NKX6A; Nkx6.1
Tractability: No criterion of Open Targets' tractability assessment is met for any kind of drug.
Gene: Protein-coding gene on chromosome 4 (84,491,985 to 84,499,292, reverse strand). Ensembl gene ENSG00000163623.
Subcellular location: Nucleus
Subcellular location (Human Protein Atlas): Nucleoplasm
Pathways (Reactome):
Developmental Biology: Developmental Lineage of Multipotent Pancreatic Progenitor Cells; Developmental Lineage of Pancreatic Acinar Cells; Developmental Lineage of Pancreatic Ductal Cells; Regulation of gene expression in beta cells; Regulation of gene expression in early pancreatic precursor cells
Gene Ontology:
Molecular function: DNA-binding transcription activator activity, RNA polymerase II-specific; DNA-binding transcription factor activity, RNA polymerase II-specific; RNA polymerase II cis-regulatory region sequence-specific DNA binding; RNA polymerase II-specific DNA-binding transcription factor binding; chromatin binding; DNA binding; DNA-binding transcription factor activity; DNA-binding transcription repressor activity, RNA polymerase II-specific; sequence-specific DNA binding
Biological process: animal organ morphogenesis; cell differentiation; glucose mediated signaling pathway; negative regulation of transcription by RNA polymerase II; pancreas development; positive regulation of transcription by RNA polymerase II; positive regulation of type B pancreatic cell development; regulation of transcription by RNA polymerase II; type B pancreatic cell maturation; type B pancreatic cell proliferation; cellular response to cytokine stimulus; cellular response to peptide hormone stimulus; neurogenesis; positive regulation of insulin secretion; regulation of DNA-templated transcription; response to nicotine; response to xenobiotic stimulus; transcription by RNA polymerase II; type B pancreatic cell development
Cellular component: extracellular exosome; chromatin; nucleus
Genetic constraint (gnomAD): Loss-of-function variants: 12 observed, 19.05 expected, observed/expected ratio (o/e) 0.63, 90% interval 0.4 to 1.02. The synonymous counts are far from expectation, so gnomAD's model fits this gene poorly and the ratio says little. Missense variants: 487 observed, 381.6 expected, observed/expected ratio (o/e) 1.28, 90% interval 1.18 to 1.38. Synonymous variants: 277 observed, 183.83 expected, observed/expected ratio (o/e) 1.51, 90% interval 1.37 to 1.66.
Homologues: Orthologues: chimpanzee NKX6-1 (100% identical), macaque NKX6-1 (99% identical), pig NKX6-1 (98% identical), dog NKX6-1 (98% identical), rabbit NKX6-1 (98% identical), mouse Nkx6-1 (96% identical), rat Nkx6-1 (96% identical), tropical clawed frog nkx6-1 (75% identical), zebrafish nkx6.1 (69% identical), Drosophila melanogaster HGTX (39% identical), Drosophila melanogaster NK7.1 (31% identical), Caenorhabditis elegans cog-1 (22% identical), and 4 more. Paralogues in human: NKX6-2 (51% identical), NKX6-3 (37% identical), NKX1-1 (19% identical), NKX1-2 (17% identical), NKX2-1 (15% identical), NKX3-2 (14% identical), NKX2-4 (14% identical), NKX2-3 (14% identical), NKX2-2 (13% identical), NKX2-6 (13% identical), NKX2-5 (13% identical), NKX3-1 (13% identical), and 1 more.
Diseases named in the same sentence as NKX6-1 in open-access papers:
NKX6-1 is named in the same sentence as 45 diseases in open-access papers, as found by Europe PMC text mining. Sharing a sentence is not in itself a finding about the gene and the disease. The quoted sentences say what the papers report.
diabetes (34 papers, 2011 to 2025). "To further explore how MAP3K15 may contribute to the pathophysiology of diabetes in pancreatic tissue, we examined its expression in transcriptomic data collected from pancreatic cell lines harboring mutations in Nkx6-1, a gene tightly associated with maturity-onset diabetes of the young (MODY)." (PMID 36383675, 2022). "In addition to NKX6–1 we found variants in WFS1, RFX6 and 7 other genes associated with monogenic forms of diabetes (AKT2, EIF2AK3, GLIS3, HADH, MNX1, NKX2–2, and PTF1A) and they may be relevant to development of MODY." (PMID 29439679, 2018). "Signature genes included previously reported beta-specific genes like NKX6-1, DLK1, and ADCYAP1 (right) and alpha cell–specific genes like IRX2, LOXL4, and DPP4, a cell surface receptor and diabetes drug target." (PMID 27864352, 2017). "We found 39 genes that were differentially regulated in common between the two NKX6–1 MODY mutants, suggesting that some of these may be related to the development of diabetes in these patients." (PMID 29439679, 2018).
Hyperglycemia (13 papers, 2013 to 2025). An increased concentration of glucose in the blood. "Similarly, transplantation of 5 x 106 HUES8-derived SC-islets (38% C-peptide+/NKX6-1+) under the kidney capsule prevented progression of hyperglycemia as early as 2 weeks post-transplant, and normalized glycemia after 12 weeks." (PMID 40831568, 2025).
type 2 diabetes (8 papers, 2021 to 2025). "Type 2 diabetes is associated with beta cell loss of identity, dedifferentiation or beta to alpha cell transdifferentiation, and can in later stages often result in loss of transcription factors such as MafA, Nkx6-1 and Pdx1." (PMID 34296320, 2021).
cervical cancer (7 papers, 2012 to 2021). A primary or metastatic malignant neoplasm involving the cervix. "In cervical cancer, NKX6-1 plays a tumor suppressive role by suppressing the epithelial-to-mesenchymal transition and cancer metastasis." (PMID 33906647, 2021). "Our findings indicated thatmethylation in the promoter regions of WT1, NKX6-1 andDBC1 is correlated with cervical cancer tumorigenesis inUygur women." (PMID 29658966, 2018). "Moreover, hypermethylation of the NKX6-1 promoter is frequently detected in leukemia, cervical cancer, ovarian cancer and colon cancer." (PMID 33906647, 2021). "For thediagnosis of cervical cancer, methylation in the promoter region ofWT1 showed a higher specificity (94.3%), sensitivity(79.4%) and positive predictive value (94.7%) than methylation in the promoterregions of NKX6-1 (88.7%, 73.5% and 89.3%) andDBC1 (79.2%, 70.6% and 80.0%)." (PMID 29658966, 2018). "The use of differential methylation hybridization using a pilot methylation array allowed the identification of SOX1, NKX6-1, PAX1, WT1, and LMX1A as frequently methylated genes in cervical cancer and precursor lesions." (PMID 34790573, 2021). "We aimed to understand the expression of WT1,NKX6-1 and DBC1 in the cervical cancer of Uygur womenin Xinjiang, and the potential of methylation markers for the screening of cervicalcancer." (PMID 29658966, 2018). "The differential methylation hybridization (DMH) using a pilot methylation array identified SOX1, NKX6-1, PAX1, WT1, and LMX1A as frequently methylated genes in cervical cancer and its precursor lesions." (PMID 22815913, 2012). "In previous studies, we discovered that SOX1, NKX6-1, PAX1, WT1, and LMX1A are highly methylated in cervical cancer." (PMID 22815913, 2012). "The expression of WT1, NKX6-1 andDBC1 genes in methylation-positive cervical cancer tissues wassignificantly lower than in methylation-negative normal cervical tissues." (PMID 29658966, 2018). "Ourresults are consistent with previous findings from other regions and ethnic groups.The methylation rate in the promoter region of NKX6-1 increasedfrom the normal cervical tissues to CIN and cervical cancer tissues, which isconsistent with other studies (Lai etal., 2008)." (PMID 29658966, 2018). "Furthermore, WT1, NKX6-1 andDBC1 genes were hypermethylated in the high-grade squamousintraepithelial lesion (CIN2, CIN3) and in the cervical cancer tissues withinfection of HPV16/18 (both P< 0.05)." (PMID 29658966, 2018). "The expression ofWT1, NKX6-1 and DBC1 was significantlylower in the methylation-positive cervical cancer tissues than inmethylation-negative normal cervical tissues." (PMID 29658966, 2018). "We analyzed statistically the relationship of themethylation rates of WT1, NKX6-1 and DBC1 withpatient age and the staging of the International Federation of Gynecology andObstetrics (FIGO), in 48 cervical cancer tissues; there was no statisticallysignificant difference." (PMID 29658966, 2018).
MODY (7 papers, 2018 to 2024). "Notably, only two mutations in NKX6-1, P329L and S317L have been described in South India and associated with MODY development." (PMID 36613572, 2022). "In addition to known MODY genes, we report the identification of variants in RFX6, WFS1, AKT2, NKX6–1 that may contribute to development of MODY." (PMID 29439679, 2018). "Twenty-three mutations were in MODY-causing genes, while five mutations were detected in potentially novel MODY-causing genes—three variants in RFX6 and two variants in NKX6-1 in seven subjects." (PMID 36613572, 2022). "We focused our investigations on 14 previously identified genes ascribed to the cause of MODY and two potentially novel MODY-causing genes, RFX6 and NKX6-1." (PMID 36613572, 2022). "A role for NKX6–1 in MODY is consistent with its role in β-cell function, maintenance and/or development and the phenotypes described in knockout mice studies." (PMID 29439679, 2018). "This suggests that S317L and P329L NKX6–1 variants were functionally impaired and that disruption of the carboxy-terminal domain of NKX6–1 is likely responsible for MODY in these individuals." (PMID 29439679, 2018). "In addition, new genes have been associated with a clinical phenotype of MODY with low penetrance, such as RFX6 (tested in our panel), a transcription factor involved in the maturation and function of the β-cell, and NKX6-1, also involved in the development of β-cells." (PMID 35769090, 2022).
insulinoma (5 papers, 2014 to 2023). "To understand these NKX6–1 variants, we functionally assessed the transcriptional activity of the NKX6–1 variants by stably expressing them or the wild-type gene in a mouse insulinoma cell line (β-TC-6), using a tetracycline inducible expression system." (PMID 29439679, 2018).
gastric cancer (4 papers, 2016 to 2020). A primary or metastatic malignant neoplasm involving the stomach. "In the study, a gastric mucosal biopsy sample was obtained from 826 patients who had undergone endoscopic resection of a gastric cancer, and DNA methylation levels of three preselected marker genes, EMX1, NKX6-1, and miR-124a-3, were measured." (PMID 26823082, 2016).
Obesity (4 papers, 2021 to 2023). Accumulation of substantial excess body fat. "Studies on obesity have shown that NK6 homeobox 1 (Nkx6.1), which binds NOTCH1 at a 139 bp enhancer sequence (known as the CR2 fragment) in the second intron and positively regulates its expression, is upregulated by lncRNA regulator of insulin transcription ROIT." (PMID 37628760, 2023).
breast carcinoma (3 papers, 2012 to 2021). "MYB is essential for mammary tumorigenesis and its upregulation is associated with estrogen receptor (ER)-positive breast cancer; NKx6-1 is a popular transcription factor involved in differentiation and development of pancreatic islet β-cells." (PMID 23056957, 2012). "In breast cancer, NKX6-1 increases IL-6 expression and promotes cell proliferation through an NKX6-1/IL-6 network." (PMID 33906647, 2021).
colorectal cancer (3 papers, 2020 to 2023). A primary or metastatic malignant neoplasm that affects the colon or rectum. "Apart from SP4, EGR1, ARID3A, and NKX6-1, the remaining transcription factors have been reported in colorectal cancer, which supports the importance of these candidate DEMs in the mechanism of CRC tumor." (PMID 36798788, 2023).
hepatocellular carcinoma (2 papers, 2020 to 2021). A malignant tumor that arises from hepatocytes. "NKX6-1 upregulates mesenchymal markers, facilitates disease progression and is associated with poor prognosis in patients with primary hepatocellular carcinoma." (PMID 33906647, 2021).
neuroendocrine tumor (2 papers, 2021 to 2022). "In addition, neuroendocrine tumor organoids were markedly enriched with the NKX6-1 regulon." (PMID 35449156, 2022). "Moreover, immunohistochemical staining for NKX6-1 could be an effective marker for pancreatic and duodenal neuroendocrine tumors." (PMID 33906647, 2021).
colon cancer (1 paper, 2021). "NKX6-1 methylation status is an indicator of survival outcome and could inform treatment selection in stage III colon cancer." (PMID 33906647, 2021).
leiomyoma (1 paper, 2021). A well-circumscribed benign smooth muscle neoplasm characterized by the presence of spindle cells with cigar-shaped nuclei, interlacing fascicles, and a whorled pattern. "We further found that NKX6-1 expression was higher in LMS (n = 19) than in nonmalignant leiomyomas (n = 14) or normal myometrium (n = 16)." (PMID 33906647, 2021).
nesidioblastosis (1 paper, 2023). "However, the key pancreatic transcription factors NK6 homeobox 1(Nkx6.1) and pancreatic and duodenal homeobox 1 (PDX1), as well as GLP-1, showed no abnormalities in nesidioblastosis patients." (PMID 37371827, 2023).
sarcoma (1 paper, 2021). A usually aggressive malignant neoplasm of the soft tissue or bone. "Importantly, inhibition of the SHH pathway significantly inhibits the growth of sarcoma cells with high NKX6-1 expression, indicating possible new treatment options for LMS patients." (PMID 33906647, 2021). "Moreover, the inconsistent effects of NKX6-1 overexpression and knockdown during cisplatin treatment in human sarcoma cells require further investigation." (PMID 33906647, 2021).
cancer (10 papers, 2017 to 2024). A tumor composed of atypical neoplastic, often pleomorphic cells that invade other tissues. "Using The Cancer Genome Atlas (TCGA) and human uterine tissue datasets, we observed that NKX6-1 expression was associated with poor prognosis and malignant potential in LMS." (PMID 33906647, 2021). "Along with the diagnostic potential of detecting NKX6-1 in cancer tissues, our findings suggest that SHH inhibitors could be applied to treat LMS." (PMID 33906647, 2021). "Whether there is a connection between the decreased expression of Nkx6-1 and the risk of cancer remains to be established." (PMID 29980752, 2018). "Droplet RNAseq analysis demonstrates that these ductal clusters express embryonic multipotent progenitor cell markers Sox9, Pdx1, and Nkx6-1, and genes involved in actin cytoskeleton regulation, inflammation responses, organ development, and cancer." (PMID 38206366, 2024). "In GE2-HCC, top potential transcriptional activators included transcription factors with reported tumour-promoting activity in HCC and/or other cancer types, e.g., NKX6-1, POU2F1/2, cJUN, E2F1, HSF2, SRF, TFCP2 and NFY." (PMID 33541355, 2021). "Although large-scale studies are needed, our study demonstrated that NKX6-1 expression regulates the cancer stemness phenotype through activation of the SHH pathway and is correlated with poor prognosis in LMS." (PMID 33906647, 2021). "Additional candidates are reported to be involved in cancer prognosis and progression, including TSPAN11, NKX6-1, and SLC16A1." (PMID 36975205, 2023). "Our results demonstrated that NKX6-1 acts through the sonic hedgehog (SHH) pathway to increase cell proliferation, drug resistance, and cancer stemness in vitro and tumorigenicity in vivo." (PMID 33906647, 2021). "Since NKX6-1 was reported to be related to stem cell differentiation, we explored the role of NKX6-1 in cancer stemness." (PMID 33906647, 2021). "In the present study, we investigated how oncogenic NKX6-1 confers poor prognosis in LMS and how NKX6-1 regulates cancer stem cells through activation of the SHH and NOTCH pathways." (PMID 33906647, 2021). "Interestingly, our study found that overexpression of NKX6-1 modulates SHH pathway genes and promotes cancer stemness, indicating a novel reciprocal regulatory axis between NKX6-1 and SHH signaling in cancer." (PMID 33906647, 2021). "Here, we have identified a relationship between NKX6-1 expression and SHH signaling activation in cancer cells and we therefore propose that SHH inhibition may represent a feasible strategy for the treatment of NKX6-1high LMS patients." (PMID 33906647, 2021). "Importantly, treatment with an SHH inhibitor (RU-SKI 43) but not a NOTCH inhibitor (DAPT) reduced cell survival in NKX6-1-expressing cancer cells, indicating that an SHH inhibitor could be useful in treating LMS." (PMID 33906647, 2021).
tumor (10 papers, 2019 to 2025). "NKX6-1 enhanced in vitro tumor cell aggressiveness via upregulation of cell proliferation and anchorage-independent growth and promoted in vivo tumor growth." (PMID 33906647, 2021). "Tumor xenograft experiments demonstrated that overexpression of NKX6-1 enhanced tumor growth in vivo." (PMID 33906647, 2021). "Compared to normal samples, the expression of E2F2, FOXJ1, EMX1, PAX7, NKX6-1, FOXD1, and ZNF552 was significantly higher (P < 0.05) and the expression of MSX1, STAT4, NR3C2, and EGR3 was significantly lower in tumor samples (all P < 0.05)." (PMID 33688372, 2021). "Two significant pathways, hsa04080, Neuroactive ligand-receptor interaction, and hsa04950, Maturity onset diabetes of the young (MODoY; with transcription factors FOXA3, NKX6-1, MAFA, PAX6, PDX1), were identified for the genes expressed more highly in the high-CCNE1 tumours." (PMID 38612869, 2024).
infection (2 papers, 2011 to 2018). The state of being infected such as from the introduction of a foreign agent such as serum, vaccine, antigenic substance or organism. "The down-regulated miR-29b and miR-29a are both or each connected to up-regulated SMARCE1, HBO1, NKX6-1, HOXA10, HBP1, OTUD4, that could be further considered as potent targets during infection." (PMID 21408164, 2011).
NKX6-1 also shares sentences with these, for which no sentence is quoted: acute lymphoblastic leukemia (3 papers); pancreatic cancer (2); viral infection (2); acute kidney injury (1); Alzheimer disease (1); astrocytoma (1); B-cell lymphoma (1); colon adenocarcinoma (1); glioblastoma (1); Glucose intolerance (1); gynecological cancer (1); Hyperinsulinemia (1); Impaired glucose tolerance (1); insulin dependent diabetes mellitus (1); Insulin resistance (1); leiomyosarcoma (1); lentivirus infection (1); maturity-onset diabetes of the young type 3 (1); metabolic disease (1); pancreatic agenesis (1); pancreatic neuroendocrine tumor (1); Parkinson disease (1); periodontitis (1); Sepsis (1); severe combined immunodeficiency (1); squamous intraepithelial lesions (1).